PDCD10 (programmed cell death 10)
Diseases named in the same sentence as PDCD10 in open-access papers (continued):
Sharing a sentence is not in itself a finding about the gene and the disease.
viral infection (2 papers, 2020 to 2025). "In addition, some of the genes involved in endothelial cell migration (ETS1, LGALS8, and PDCD10) are also known to be associated with perturbations during viral infection." (PMID 33240937, 2020). "We also noted that the mRNA levels of IFNB, ISG56, RANTES, and CXCL10 in PDCD10-knockdown cells were increased after viral infection." (PMID 41296880, 2025). "To further confirm the effect of PDCD10 on innate immune response, we assessed IFN-β promoter activation in PDCD10-knockout cells (PDCD10 KO cells, PDCD10-/-) during viral infection." (PMID 41296880, 2025). "IFN-β promoter activation was inhibited by PDCD10 in a dose-dependent manner in HEK293 cells after virus infection." (PMID 41296880, 2025). "The underlying mechanism was that PDCD10 disrupted the formation of a complex between VISA and IRF3 during viral infection." (PMID 41296880, 2025). "In the present study, we demonstrated that virus infection slightly increased the expression of programmed cell death protein 10 (PDCD10)." (PMID 41296880, 2025). "The present study showed that PDCD10 expression was slightly increased by virus infection, while PDCD10 promoted FMDV replication." (PMID 41296880, 2025). "During the viral infection process, FMDV also uses PDCD10 to further inhibit IFNβ production and promote FMDV replication." (PMID 41296880, 2025).
astrocytoma (1 paper, 2015). "mRNA and protein expression of PDCD10 were examined respectively by real-time RT-PCR and Western blotting in GBM (n = 27), astrocytoma grade II (n = 13) and control (n = 11)." (PMID 26490252, 2015).
cerebral lesions (1 paper, 2014). "In particular, PDCD10-GCKIII signalling facilitates lumen formation by endothelial cells, which is important during the progression of cerebral lesions and these kinases are important for the regulation of apoptosis, cell proliferation, polarity, migration, and cytoskeleton remodelling." (PMID 25354366, 2014).
esophageal carcinoma (1 paper, 2022). A primary or metastatic malignant neoplasm involving the esophagus. "We used the TISDB database to investigate the relationship of PDCD10 expression with a wide range of tumor molecular subtypes and discovered that it was positively correlated with esophageal carcinoma (ESCA), lung squamous cell carcinoma (LUSC), and stomach adenocarcinoma (STAD) (p < 0.05)." (PMID 36276268, 2022).
intracerebral hemorrhage (1 paper, 2025). A cerebrovascular disorder characterized by bleeding into one or both cerebral hemispheres including the basal ganglia and the cerebral cortex. "The condition is caused by mutations in KRIT1 (CCM1), CCM2 (malcavernin), or PDCD10 (CCM3) and may lead to intracerebral hemorrhage (ICH) or non-hemorrhagic focal neurological deficits (FNDs), potentially leading to severe disability and even death." (PMID 41561324, 2025).
liver disease (1 paper, 2024). "The results shed new light on the role of MST3, STK25, and MST4, as well as their interactions with PDCD10, MAP4K4, and HSD17B11, in the control of liver lipid homeostasis and metabolic dysfunction–associated steatotic liver disease susceptibility." (PMID 39395791, 2024).
ovarian adenocarcinoma (1 paper, 2020). An adenocarcinoma that arises from the ovary. "All types of ovarian adenocarcinomas showed increased expression levels of PDCD10 compared with the normal ovary." (PMID 32483426, 2020).
pancreatic cancer (1 paper, 2024). "Furthermore, it suggested that PROSER2 may inhibit the growthand metastasis of pancreatic cancer cells and regulate its mechanismthrough binding with STK25 and the PDCD10 complex." (PMID 38293943, 2024).
pituitary adenomas (1 paper, 2022). "Moreover, PDCD10 significantly promoted epithelial–mesenchymal transition (EMT) of pituitary adenoma cells." (PMID 35963638, 2022).
Polyuria (1 paper, 2021). An increased rate of urine production. "Here, we found that mice deficient of Pdcd10 or Stk24/25 in the kidney tubules developed polyuria and displayed increased water consumption." (PMID 34156031, 2021).
schizophrenia (1 paper, 2022). A major psychotic disorder characterized by abnormalities in the perception or expression of reality. "Among these STRIPAK genes of the PPI network, PDCD10 (Programmed Cell Death 10) is an eQTL gene associated with schizophrenia risk." (PMID 35886854, 2022). "The protein-protein interaction (PPI) networks found two main clusters having schizophrenia expression quantitative trait loci (eQTL) genes such as PDCD10, ANK2, and AKT3, suggesting further investigation on these genes as potential novel treatment targets." (PMID 35886854, 2022). "To complement the robustness of finding therapeutic relevant gene targets, we compared with evidence from GWAS and found three schizophrenia-associated eQTL genes in the two main clusters of the PPI networks (i.e., PDCD10 and AKT3 in cluster 1, ANK2 in cluster 2)." (PMID 35886854, 2022). "Some schizophrenia eQTL genes such as PDCD10, ANK2 and AKT3 with highly connected functions to these pathways should be further investigated to find out how they and their related pathways are involved with the disease, which might potentially enable the finding of novel treatment targets." (PMID 35886854, 2022).
scoliosis (1 paper, 2016). A congenital or acquired spinal deformity characterized by lateral curvature of the spine. "Moreover, these authors found additional PDCD10 aberrations in addition to the CCMs, including scoliosis, cognitive disability, and skin lesions, further suggesting that PDCD10 plays other roles in tissue development aside from endothelial cell formation." (PMID 27896269, 2016).
small intestine cancer (1 paper, 2007). A primary or metastatic malignant neoplasm involving the small intestine. "Furthermore, when we investigated the expression patterns of PDCD10 in other normal and cancerous tissues, we found that PDCD10 was up-regulated in various cancers including ovarian, stomach, lung, uterus and small intestine cancers." (PMID 17212813, 2007).
tumor (46 papers, 2007 to 2026). "Loss of PDCD10 in CAFs remodels the extracellular matrix network and eventually causes changes in tumor stiffness and increased metastatic spread, via a positive feedback loop between mechanotransduction and YAP signaling." (PMID 36497468, 2022). "Previous report indicated that loss of PDCD10 in GBM activated tumor cell behaviors and mediated chemotherapy resistance." (PMID 34108959, 2021). "Correlation analysis using TCGA HCC data showed that PDCD10 was markedly correlated with many Hippo downstream effectors associated with tumour proliferation, migration, invasion, and EMT." (PMID 34521817, 2021). "In the training cohort, PDCD10 expression was significantly associated with tumour number, tumour size, MVI, capsular formation, Edmondson-Steiner grade, TNM stage and BCLC stage (all with P < 0.05)." (PMID 34521817, 2021). "As a result, PDCD10 expression in homograft tumor was positively associated with the number of infiltrated microglia/macrophages in both tumor edge and tumor core." (PMID 34108959, 2021). "Based on the paracrine mechanism and the direct interaction between tumor cells and TAMs, our present study aimed to explore the potential impact of PDCD10 in GBM on GAMs and the underlying mechanism." (PMID 34108959, 2021). "PDCD10 overexpression can accelerate tumor migration, invasion through reversing TRIM59 loss-induced contractile phenotypes." (PMID 34733794, 2021). "PDCD10 is potentially implicated in tumor proliferation and apoptosis, hyperangiogenesis and peritumoral edema in GBM." (PMID 26490252, 2015). "Programmed cell death 10 (PDCD10) plays a pivotal role in regulating apoptosis, neoangiogenesis and vessel permeability and is implicated in certain tumor signaling pathways." (PMID 26490252, 2015). "To further investigate the association of PDCD10 expression and the status of tumor cells, i.e., proliferation or apoptosis, we performed double staining of PDCD10/PCNA and PDCD10/caspase 3 (active form)." (PMID 26490252, 2015). "Loss of PDCD10 immunoreactivity was identified in proliferating tumor and vascular endothelial cells as well as in tumor cells." (PMID 26490252, 2015). "ICCA cells-released exosomes harboring miR-30a-5p induced tumor-associated angiogenesis and elevated endothelium permeability, ultimately facilitating invasive behavior of cancer cells to endothelium and subsequent hematogenous metastasis by targeted PDCD10." (PMID 37781039, 2023). "The dysfunction of PDCD10 has been strongly implicated in oncogenesis and tumor progression." (PMID 36497468, 2022). "PDCD10 has also been linked to tumor formation and the initiation of other biological processes." (PMID 36276268, 2022). "The association of PDCD10 downregulation with the activation of Akt, with hyper-angiogenesis and with higher a grade of peritumoral edema suggests a potential function of PDCD10 in tumor cell survival, angiogenesis and in regulating vessel integrity." (PMID 26490252, 2015). "The PDCD10 expression level was reported to be associated with tumor stage and nodal involvement in various cancer types, suggesting that PDCD10 may promote tumor metastasis." (PMID 36497468, 2022). "Here, we demonstrate that the loss of PDCD10 causes a significant TMZ-resistance during treatment and promotes a rapid regrowth of tumor cells after treatment." (PMID 39273014, 2024). "PDCD10 inhibited tumor cell apoptosis and promoted tumor progression through activating EMT pathway." (PMID 35848121, 2023). "At present, relative researches on PDCD10 mainly focus on tumors, and the findings have confirmed that PDCD10 can promote the process of tumor." (PMID 35848121, 2023). "We revealed the potential role of PDCD10 as a prognostic indicator for patients with different tumor types and its potential role in affecting tumor immunotherapy efficacy by affecting TME." (PMID 36276268, 2022).
tumor (continued). "Downregulation of PDCD10 in tumor cells promoted the capillary tube formation of human umbilical vein endothelial cells and tumor angiogenesis." (PMID 36497468, 2022). "Previous study was founding the tumor-suppressing effects of miR-222-3p have shown that miR-222-3p inhibited the level of PDCD10 to decrease the tumor metastasis via regulating Wnt/β-catenin signaling pathway in ovarian cancer." (PMID 35585935, 2022). "Activation of CXCR2 inversed inactivation of AKT/ERK signal pathways and the tumor-suppressive effects induced by PDCD10 silencing." (PMID 35963638, 2022). "Consistent with the results from the in vitro experiments, PDCD10 silencing significantly reduced the tumor sizes and weights of xenograft tumors (Att-20 cell line: 0.94±0.07g vs. 0.38±0.06g, and TtT/GF cell line:1.04±0.11g vs. 0.34g±0.12g)." (PMID 35963638, 2022). "Given the negative regulation of GCKIII kinases mediated by PP2A, it seems paradoxical that PDCD10 not only enhances the catalytic activity of PP2A but also stabilizes GCKIII kinases in tumor cells." (PMID 36497468, 2022). "We analyzed PDCD10 expression in various tumor types and discovered that it is upregulated in malignancies and inversely connected with CAF." (PMID 36276268, 2022). "In cancer-associated fibroblasts (CAFs), loss of PDCD10 promoted the nuclear translocation of YAP via interacting with paxillin, which contributed to tumor metastasis." (PMID 36497468, 2022). "PDCD10 promotes cell migration and tumor metastasis through epithelial-mesenchymal transition and the Wnt signaling pathway and is involved in apoptosis and cell cycle regulation." (PMID 36071474, 2022). "PDCD10 expression in AML was strongly positively connected with EMT, which agree with previous studies that have linked PDCD10 expression to tumor functional state." (PMID 36276268, 2022). "In recent years, accumulating evidence has shown that dysregulation of PDCD10 was closely related to tumorigenesis and progression in diverse tumor types." (PMID 35963638, 2022). "We also evaluated the immunological, clinical, and genetic aspects of distinct cancers by using TIMER2.0 and the connection between PDCD10 expression and tumor immune subtypes by using TISDB." (PMID 36276268, 2022). "PDCD10 is widely expressed in various types of cells, such as astrocyte, neuron, endothelial cells and tumor cells." (PMID 34108959, 2021). "Intriguingly, the aggressive tumor growth and increase of microglia/macrophage recruitments induced by Pdcd10 upregulation were reversed by the treatment with SB225002." (PMID 34108959, 2021). "Expression levels of HMGA2 and PDCD10 in CHOL were significantly correlated with tumor infiltration by seven and nine immune cell types, respectively." (PMID 34831096, 2021). "Knocking down PP2Ac abolished the tumour-promoting role of PDCD10 in the migration, invasion and EMT of HCC." (PMID 34521817, 2021). "Altered expression of PDCD10 had been reported in various tumors including breast cancer, prostate cancer, bladder cancer etc., playing dual function in tumor progression and chemo-therapy resistance." (PMID 34108959, 2021). "Studies from the Zhu group indicate that PDCD10 plays a tumour suppressor role in glioblastoma by inhibiting growth and invasion." (PMID 34521817, 2021). "A recent publication demonstrates that loss of PDCD10 in GBM promotes cellular behaviors and tumor progression." (PMID 34108959, 2021). "Knockdown of PDCD10 in Hep3B cells significantly inhibited tumour growth, and PDCD10 overexpression in HepG2 cells promoted the growth of subcutaneous tumours." (PMID 34521817, 2021). "To further explore the role of PDCD10 in vivo, we first established a subcutaneous xenograft tumour model." (PMID 34521817, 2021). "As expected, upon knockdown of PDCD10 TCs activated themselves toward a more aggressive phenotype and promoted tumor growth." (PMID 32850441, 2020).
tumor (continued). "We demonstrated that downregulation of PDCD10 in human primary GBM was associated with the activation of Akt, higher tumor microvessel density, and higher grade of peritumoral edema." (PMID 32850441, 2020). "(C) Heatmap of average logFC (padj <0.05) for Pdcd10-ko vs. Pdcd10-wt for selected tumor tip cell markers (as indicated)." (PMID 33138917, 2020). "It is also demonstrated that as downstream target of miRNAs, PDCD10 is involved in the tumor phenotype and chemo-resistance." (PMID 32850441, 2020). "To monitor the effect of miR-222-3p and PDCD10 expression on tumor metastasis, we used the In-vivo imaging system to analyze the images of lung and luminescent tissues." (PMID 32483426, 2020). "On the contrary, PDCD10 overexpression regulated the expression of downstream targets and promoted cancer cell migration and tumor metastasis, which suggested a pro-oncogenic role of the PDCD10." (PMID 32483426, 2020). "Further study of the interaction between ECs and GBM cells (TCs) indicated that PDCD10-ablation in ECs activated proliferation-, adhesion-, invasion-, and migration of TCs in vitro and promoted neo-angiogenesis and tumor growth in xenograft models." (PMID 32850441, 2020). "More importantly, the treatment with NVP not only abolished PDCD10-knockdown-mediated activation of EphB4, but also suppressed the aggressive tumor progression and rapid growth in shPDCD10 mice." (PMID 32850441, 2020). "Conversely, C9 Pdcd10-ko cells showed up-regulation of a large set of tumor tip cell markers, which were less modified in C1 and C6." (PMID 33138917, 2020). "As far as angiogenesis is concerned, the role of the endothelium and its interaction with GBM cells have been explored by LV-shRNA, disclosing the role of programmed cell death protein 10 (PDCD10) dysregulation in tumor angiogenesis and in GBM progression." (PMID 30909628, 2019). "Remarkably, knock‐down of endothelial CCM3/PDCD10 largely stimulated neo‐angiogenesis and promoted tumour growth through a paracrine mechanism." (PMID 28371279, 2017). "Further investigation is required to uncover the direct role and the underlying signaling of PDCD10 deficiency in GBM, which will extend our understanding on the function of PDCD10 in this tumor." (PMID 26490252, 2015). "The expression of PDCD10 was correlated to the tumor cell survival signaling protein p-Akt, to microvascular density and peritumour edema in GBM." (PMID 26490252, 2015). "Moreover, a loss of PDCD10 in endothelial cells activated GBM cells via a paracrine mechanism, demonstrating its central role in the crosstalk between tumor cells and endothelial cells." (PMID 39273014, 2024). "Thus, these PDCD10-depleted cells are reminiscent of the tumor-initiating cells that are responsible for tumor growth." (PMID 39273014, 2024). "GSCs derived from PDCD10 knockdown cells displayed stronger TMZ-resistance and regrowth potency, compared to their parental counterparts, indicating that PDCD10-induced stemness may independently contribute to tumor malignancy." (PMID 39273014, 2024). "Tumors injected with PDCD10 overexpressing cells had significantly increased tumor size and weight." (PMID 35848121, 2023). "In addition, PDCD10 can not only inhibit tumor cell proliferation but also prevent cell apoptosis under different conditions." (PMID 35848121, 2023). "Through bioinformatics analysis, we predicted that PDCD10 may affect related signaling pathways in tumor progression." (PMID 35848121, 2023). "PDCD10 inhibited tumor cell apoptosis and promoted tumor progression by activating the EMT pathway." (PMID 35848121, 2023). "Furthermore, the expression of PDCD10 was examined between non-invasive and invasive PA tumor samples which were collected from the Neurosurgery department at Tongji Hospital." (PMID 35963638, 2022). "Our lab has previously reported that miR-222-3p could target GNAI2 to inhibit tumor proliferation and target PDCD10 to inhibit cell migration in OC." (PMID 35451651, 2022).